RUNX1T1 (RUNX1 partner transcriptional co-repressor 1)
Diseases named in the same sentence as RUNX1T1 in open-access papers (continued):
Sharing a sentence is not in itself a finding about the gene and the disease.
acute promyelocytic leukemia (20 papers, 2014 to 2025). An aggressive form of acute myeloid leukemia (AML), characterized by arrest of leukocyte differentiation at the promyelocyte stage, due to a specific chromosomal translocation t(15;17) in myeloid cells. "The miR-181 cluster (miR-181a-3p, -5p and b-3p) showed a varied expression in their AML patients; in particular, it was high in the RUNX1/RUNX1T1-positive AML subtype, whereas only miR-181a-5p showed a steep increase in acute promyelocytic leukemia, where miR-181a-3p was usually downregulated." (PMID 33330086, 2020). "Importantly, PCR assays have been developed for three AML phenotypes: (i) acute promyelocytic leukemia (APL) (fusion gene PML::RARA); (ii) patients with NPM1 and CBF–AML (RUNX1::RUNX1T1 and CBFB::MYH11); and (iii) AML with fusion genes BCR::ABL1, KMT2::MLLT3, and DEK::NUP214." (PMID 37345204, 2023). "Assays have been developed for three phenotypes of particular clinical significance: NPM1, Core Bind Factor (CBF)-AML (referring to the fusions gene RUNX1::RUNX1T1 and CBFB::MYH11) and Acute Promyelocytic Leukemia (APL) (referring to the fusion gene PML::RARA)." (PMID 35892893, 2022). "A case of acute promyelocytic leukemia (APL) with RUNX1T1 insertion to 7q is described and compared to reported cases of APL with negative retinoic acid receptor alpha (RARA) abnormality." (PMID 26351594, 2015).
acute leukemia (14 papers, 2010 to 2025). A clonal (malignant) hematopoietic disorder with an acute onset, affecting the bone marrow and the peripheral blood. "In our clinical practice, we noted cases of AML with various RUNX1 lesions (beyond RUNX1::RUNX1T1 fusion and RUNX1 mutations) with aberrant expression of several B-cell markers, mimicking mixed-phenotype acute leukemia (MPAL)-B/myeloid at diagnosis." (PMID 40282530, 2025). "Amongst acute leukemia patients in our cohort, one patient had RUNX1::RUNX1T1 translocation, while another had a biallelic CEBPA mutation, both of which are known to co-occur with CSF3R alterations." (PMID 40806796, 2025).
myeloid leukemia (13 papers, 1999 to 2026). A clonal proliferation of myeloid cells and their precursors in the bone marrow, peripheral blood, and spleen. "NHR1, also referred to as TAFH, is a hub for interaction with several transcription regulators and is required for transforming ability of RUNX1/RUNX1T1 fusion in myeloid leukemia." (PMID 39478125, 2024). "Indeed, knockdown of RUNX1/RUNX1T1 with small interfering RNA (siRNA) decreased NTAL expression in Kasumi-1 cells, a myeloblast cell line widely used as a model for the study of myeloid leukemias." (PMID 36902005, 2023).
breast carcinoma (7 papers, 2011 to 2024). "Conversely, in the domain of breast cancer, an elevated expression of RUNX1T1 facilitates RBM24‐induced tumour cell proliferation, thereby fostering tumour progression." (PMID 38894657, 2024). "RUNX1T1 is collectively viewed as a biomarker for primary pancreatic endocrine tumors (PETs), breast cancer, and colorectal cancer (CRC) and a strong indicator of patient prognosis." (PMID 35902872, 2022).
ovarian carcinoma (7 papers, 2015 to 2024). A malignant neoplasm originating from the surface ovarian epithelium. "RUNX1t1 is also a candidate tumor suppressor in ovarian cancer and loss of RUNX1t1 expression has been associated with metastasis in pancreatic cancer." (PMID 27522676, 2016). "In recent studies, RUNX1T1 has been shown to be more likely to function as a suppressor during the advance of gastric tumors, gliomas, and ovarian cancer." (PMID 35902872, 2022). "In ovarian cancer, RUNX1T1, which is believed to inhibit the proliferation, migration, and invasion of ovarian cancer cells, is promoted when the long non-coding RNA (IncRNA) EPB41L4A-AS2 is overexpressed." (PMID 35902872, 2022). "IncRNA sequesters functions by binding with miR-103a to increase RUNX1T1 expression, highlighting the effects of RUNX1T1 and effectively delays ovarian cancer progression." (PMID 35902872, 2022). "RUNX1T1 was frequently hypermethylated in ovarian tumors with high clinical stages and primary ovarian cancer-initiating cells." (PMID 29046615, 2017). "RUNX1t1 promoter hypermethylation has also been observed in ovarian cancer and thus suggests an alternative route of RUNX1t1 gene silencing in carcinogenesis." (PMID 27522676, 2016). "Our previous studies demonstrated that novel TGF-β targets, FBXO32 and RunX1T1, are epigenetically silenced by promoter hypermethylation in ovarian cancer." (PMID 25628764, 2015). "Enhanced RUNX1T1 expression inhibited ovarian cancer cell growth." (PMID 29046615, 2017). "The eventual correlation between RUNX1T1 and HDAC5 in the acquisition of platinum resistance in ovarian cancer should be studied in detail." (PMID 37686015, 2023).
glioma (5 papers, 2017 to 2022). A benign or malignant brain and spinal cord tumor that arises from glial cells (astrocytes, oligodendrocytes, ependymal cells). "In human glioma patient tissues, the expression of the RUNX1T1 gene and protein is downregulated, while the expression of HIF-1α is higher than that in normal brain tissues." (PMID 36231060, 2022). "Thus, the progression and prognosis of gliomas probably correlate with RUNX1T1 as a core regulator in glioblastoma cell proliferation." (PMID 35902872, 2022). "In glioma, RUNX1T1 has been viewed as a potential biomarker and possible target due to its interaction with Hypoxia-inducible factor 1α (HIF1α), which is closely related to the proliferation, survival, self-renewal, and invasiveness of glioma stem cells." (PMID 35902872, 2022). "The driver genes and pathways identified herein such as MSH6 and RUNX1T1 might be candidate prognostic biomarkers and therapeutic targets in glioma." (PMID 29046615, 2017). "The driver genes such as MSH6 and RUNX1T1 might serve as candidate prognostic biomarkers and therapeutic targets in glioma." (PMID 29046615, 2017). "Though the research on RUNX1T1, FKBP3, and PH21A in glioma was definite, the signature was annotated as “chromatin binding” by the functional enrichment analysis." (PMID 34540896, 2021). "In the signature, HDAC1 (HR:1.4938) and RBL1 (HR:1.7148) were deemed a hazard, while RUNX1T1 (HR:0.7349), FKBP3 (HR:0.6382), and PHF21A (HR:0.4956) promoted survival possibilities for glioma patients." (PMID 34540896, 2021). "Of these TFGs, the role of TCF12, RUNX1T1, and LMNA in gliomas is still unclear and needs further investigation." (PMID 32695826, 2020). "On the contrary, 43 driver genes were down-regulated expression and related to favorable clinical outcomes in glioma patients, such as PIK3R1, FLT3, PIK3R1 and RUNX1T1." (PMID 29046615, 2017). "Moreover, RUNX1T1 reportedly interacts with HIF-1α and recruits proline hydroxylase 2 (PHD2) and GSK3β for HIF-1α degradation, resulting in the inhibition of glioma cells." (PMID 36231060, 2022).
lung carcinoma (4 papers, 2012 to 2021). "The association between RUNX1T1 and lung cancer is unclear, but its binding partner RUNX1 was overexpressed in non-small-cell lung cancer." (PMID 32258117, 2020). "The results showed that CCNE1, E2F1, ARHGAP11A, RUNX1T1 and FES were significantly associated with patient survival in lung cancer (n = 1925)." (PMID 33613291, 2021). "Validation experiments in multiple lung cancer cell lines showed that RUNX1T1 overexpression consistently decreased CDKN1A (p21) expression and increased E2F transcriptional activity, which is commonly altered in SCLC." (PMID 33084222, 2021). "To explore potential downstream function(s) of RUNX1T1, we used lentivirus to stably overexpress RUNX1T1 in five lung cancer cell lines with low endogenous RUNX1T1 expression (A549, H16450, H841, SW1271, H1299) to create models of RUNX1T1 amplification." (PMID 33084222, 2021). "RUNX1T1 interacts with the CDKN1A (p21) promoter and is associated with reduced histone H3 acetylation, resulting in decreased p21 expression and increased E2F transcriptional activity in lung cancer cell lines." (PMID 33084222, 2021). "Because the role of RUNX1T1 by itself as a nonfusion protein has rarely been examined in cancer, including lung carcinoma, we sought to determine whether RUNX1T1 could contribute to the SCLC phenotype and if so, its mechanism of action." (PMID 33084222, 2021). "Furthermore, an epigenetic role for RUNX1T1 by itself as a nonfusion protein has rarely been examined in cancer; thus, any finding in lung carcinoma would be novel." (PMID 33084222, 2021).
melanoma (4 papers, 2019 to 2025). A malignant, usually aggressive tumor composed of atypical, neoplastic melanocytes. "Gene set enrichment analysis (GSEA) of all DEGs demonstrated marked functional disparities between AS and control samples, particularly in targets of RUNX1 RUNX1T1 fusion erythrocyte, melanoma, β-IFN–treated bronchial epithelial cells, Class A1 rhodopsin-like receptors, and tumor rejection." (PMID 40894479, 2025).
bladder cancer (3 papers, 2021 to 2022). "The enhancement of RUNX1T1 mRNA causes a cascade reaction of the loop, causing RBM24 upregulation, further promoting bladder cancer progression." (PMID 35902872, 2022). "RUNX1T1 is also involved in the progression of bladder cancer via the positive RUNX1T1/TCF4/miR-625-5p feedback loop, closely relating to RNA-binding motif protein 24 (RBM24), a determinant of carcinogenesis." (PMID 35902872, 2022). "For example, it stabilizes PTEN mRNA in CRC to prevent tumor growth but increases RUNX1T1 expression to drive bladder cancer progression." (PMID 35406615, 2022). "Recent studies show that by binding to the 3′-UTR, RBM24 stabilizes RUNX1T1 (RUNX1-related transcription factor 1) mRNA in bladder carcinoma and PTEN (phosphatase and tensin homolog) mRNA in colorectal cancer (CRC), with opposite effects on tumor progression." (PMID 35406615, 2022). "Functional analyses using human bladder carcinoma cells indicate that RBM24 stabilizes RUNX1T1 mRNA and increases the expression of RUNX1T1 protein, which in turn positively regulates RBM24 expression by suppressing the transcription of its inhibitory miR-625-5p." (PMID 35406615, 2022). "Even though RUNX1T1 is downregulated in most cases of carcinogenesis, its upregulation has also been revealed in research on small cell lung cancer (SCLC) and bladder cancer." (PMID 35902872, 2022). "In gastric cancer, the role of RUNX1T1 is related to C/EBPβ, which is overexpressed in AML, gastric, skin and bladder cancer." (PMID 35902872, 2022).
glioblastoma (3 papers, 2015 to 2023). The most malignant astrocytic tumor (WHO grade IV). "Also related to the genes identified in the platinum resistance setting in this work, the downregulation of the transcription factor RUNX1T1, and its associated upregulation of Hypoxia-inducible factor 1α (HIF1α), has been associated with the severity and drug resistance in glioblastoma." (PMID 37686015, 2023). "In T98G glioblastoma cell line we found a combination of 4 miRNAs (miR-30e-3p, miR-3605-5p, miR-4762-5p, miR-4768-5p) which are targeting the same gene, RUNX1T1, and a combination of 3 miRNAs (miR-4768-5p, miR-375, miR-5701) targeting the HHIP gene (darker green squares)." (PMID 34157951, 2021). "Here we report for the first time the variable gene expression behavior of RUNX1T1 and HHIP related to tumor location within a glioblastoma context." (PMID 34157951, 2021). "Finally, we focused our attention on RUNX1T1 and HHIP gene, the genes more affected by the exosome-derived miRNAs in glioblastoma cell lines subjected to invasion." (PMID 34157951, 2021).
lung adenocarcinoma (3 papers, 2021 to 2024). A carcinoma that arises from the lung and is characterized by the presence of malignant glandular epithelial cells. "BRAF non-Val600 mutations and RUNX1T1 amplifications seem to be unusually prevalent and ALK fusions rare in Finnish lung adenocarcinoma patients." (PMID 35964518, 2022). "Gene mutations observed differ between lung adenocarcinoma and lung squamous cell carcinoma, with KRAS, EGFR, LPHN3, KEAP1, and TLR4 being relatively common in lung adenocarcinoma, whereas BAI3, FBXW7, GRM8, ERBB4, MUC16, and RUNX1T1 are common in lung squamous cell carcinoma." (PMID 39594843, 2024). "SCLC specimens showed a range of RUNX1T1 positivity, in contrast with lung adenocarcinoma and lung squamous cell tumors, where little to no RUNX1T1 signal was detected." (PMID 33084222, 2021).
lymphoma (3 papers, 2014 to 2024). A malignant (clonal) proliferation of B- lymphocytes or T- lymphocytes which involves the lymph nodes, bone marrow and/or extranodal sites. "Interestingly, RUNX1T1 was shown to regulate motility and tube forming ability of endothelial cells, supporting its potential involvement in migration and invasion of lymphoma cells." (PMID 39478125, 2024). "In addition, we found recurrent somatic mutations in the protein phosphatase 1 regulatory subunit 9 A (PPP1R9A), in FAT cadherins, and in the RUNX1T1 transcriptional repressor, suggesting their possible involvement in shaping the phenotype of lymphoma cells." (PMID 39478125, 2024).
neuroblastoma (3 papers, 2022 to 2025). Neuroblastoma (NB) is the most common solid, extracranial childhood tumor. "Using an unbiased large-scale mutagenesis screen in neuroblastoma-prone transgenic mice, we identify a single germline point mutation in the transcriptional corepressor Runx1t1, which abolishes MYCN-driven tumorigenesis." (PMID 38992040, 2024). "Deletion of one Runx1t1 allele in an independent Runx1t1 knockout mouse model is also sufficient to prevent MYCN-driven neuroblastoma development, and reverse ganglia hyperplasia, a known pre-requisite for tumorigenesis." (PMID 38992040, 2024). "Silencing RUNX1T1 in human neuroblastoma cells decreases colony formation in vitro, and inhibits tumor growth in vivo." (PMID 38992040, 2024). "Together, these results highlight a role for RUNX1T1 in tumor initiation and in vivo neuroblastoma cell growth." (PMID 38992040, 2024). "Here, the authors identify that the transcriptional corepressor Runx1t1 is indispensable for MYCN-driven neuroblastoma tumorigenesis." (PMID 38992040, 2024). "We also demonstrate this loss-of-function effect in an independent Runx1t1 knockout mouse model, and via in vitro and in vivo studies silencing RUNX1T1 in human neuroblastoma cells." (PMID 38992040, 2024). "Neuroblastoma samples as a group had higher RUNX1T1 levels compared to the more benign forms of ganglioneuroblastoma and ganglioneuroma." (PMID 38992040, 2024). "Altogether, these results provide evidence for RUNX1T1 being required to maintain a MYCN-driven ESC-like phenotype characteristic of aggressive MYCN-amplified neuroblastoma." (PMID 38992040, 2024). "In this work, we show that RUNX1T1 forms part of a repressive complex in neuroblastoma cells acting on enhancer regions to support MYCN and HAND2 in driving neuroblast hyperplasia and eventual transformation." (PMID 38992040, 2024). "Altogether, these data provide evidence for recruitment by HAND2 of a RUNX1T1 repressor complex to help maintain an undifferentiated phenotype in MYCN-amplified neuroblastoma cells." (PMID 38992040, 2024). "Here, we identify using ENU mutagenesis of Th-MYCN mice a pedigree harboring a single loss-of-function mutation in the co-repressor Runx1t1, which segregates with abolition of MYCN-driven neuroblastoma tumorigenesis." (PMID 38992040, 2024). "To explore whether RUNX1T1 plays a role in the maintenance of established neuroblastomas, we generated cell lines with doxycycline-inducible shRNA knockdown of this co-repressor." (PMID 38992040, 2024). "Interrogation of the Cancer Cell Line Encyclopedia45 showed that neuroblastoma, SCLC, and sarcoma had the highest levels of RUNX1T1 expression compared to all other tumor types." (PMID 38992040, 2024). "We observed high-level RUNX1T1 expression in five SCLC cell lines by comparison with the non-small cell lung cancer A549 cells and SH-SY5Y neuroblastoma cells." (PMID 38992040, 2024). "To determine if RUNX1T1 is regulated by MYCN, we analysed RUNX1T1 protein and RNA expression in the human SH-EP Tet-21/N cell line, a non-amplified neuroblastoma line with a MYCN doxycycline-off inducible construct." (PMID 38992040, 2024).
non-small cell lung carcinoma (3 papers, 2020 to 2024). A group of at least three distinct histological types of lung cancer, including non-small cell squamous cell carcinoma, adenocarcinoma, and large cell carcinoma. "One group has previously reported RUNX1T1 amplification in combined small cell and non-small cell lung cancer." (PMID 35964518, 2022).
Obesity (3 papers, 2018 to 2022). Accumulation of substantial excess body fat. "A recent study reported that RUNX1T1 is an inhibitor of brown adipogenesis (associated with a lean and healthy phenotype), which was associated with obesity and suggested that the miRNAs that downregulates this TF could be part of novel therapeutics to increase BAT (brown adipose tissue) in humans." (PMID 29945546, 2018).
chloroma (2 papers, 2021 to 2025). "The backward elimination procedure identified RUNX1T1, MAPK3, PIK3CG, TCF7L1, GRB2, and MTOR as the empirical drivers of the association with chloroma." (PMID 33882829, 2021).
colorectal cancer (2 papers, 2014 to 2017). A primary or metastatic malignant neoplasm that affects the colon or rectum. "The expression of RUNX1T1 was severely down-regulated in colorectal cancer (CRC), increased expression of RUNX1T1 suppressed cellular proliferation and sensitized CRC cells to 5-fluorouracil." (PMID 29046615, 2017).